KLF14 (KLF transcription factor 14)
Diseases named in the same sentence as KLF14 in open-access papers (continued):
Sharing a sentence is not in itself a finding about the gene and the disease.
Sepsis (6 papers, 2022 to 2024). Sepsis is defined as life-threatening organ dysfunction caused by a dysregulated host response to infection. "KLF14 deficiency is associated with significantly increased mortality in endotoxemia and sepsis models in mice, whereas the pharmacological activation of KLF14 confers protection against sepsis in these murine models." (PMID 39712019, 2024). "To determine the role of KLF14 in the immune function of macrophages during sepsis, we first assessed the expression of KLF14 in in vivo and in vitro murine sepsis models." (PMID 34983946, 2022). "Our studies have identified the regulatory role of KLF14 in the immune response of macrophages during sepsis." (PMID 34983946, 2022). "We provide evidence to support that KLF14 can inhibit glycolysis in macrophages by suppressing HK2 transcription during sepsis." (PMID 34983946, 2022). "We sought to further understand the role of KLF14 in the regulation of the inflammatory response in sepsis, and we first observed the increased expression of KLF14 in sepsis patients and mice." (PMID 34983946, 2022). "Here, our data indicate that the KLF14-HK2 signaling pathway can affect the immune function of macrophages, suggesting that KLF14 is a potential therapeutic target for sepsis." (PMID 34983946, 2022). "In summary, our findings demonstrate that KLF14 plays an yet unrecognized role in the immune function of macrophages in sepsis, and thus, targeting KLF14 is a potential therapeutic strategy for sepsis." (PMID 34983946, 2022). "KLF14 deletion led to significantly increased mortality in lethal models of murine endotoxemia and sepsis." (PMID 34983946, 2022). "To further understand the effect of KLF14 on the macrophage immune response during sepsis, we performed transplant experiments by using WT C57BL/6 mice as recipients." (PMID 34983946, 2022). "Taken together, these results indicated that perhexiline, as an agonist of KLF14, has a potential role in the management of sepsis." (PMID 34983946, 2022). "In lethal models of murine sepsis and endotoxemia, the expression of KLF14 was increased in PBMCs and various tissues of septic mice." (PMID 34983946, 2022). "We further analyzed the biological information of patients with sepsis in the GEO database, and the results showed that the expression of KLF14 in sepsis patients was significantly higher than that in the control group." (PMID 34983946, 2022). "Here, we provide evidence to support the function of KLF14, a novel Krüppel-like transcription factor, in the regulation of glycolysis and the immune function of macrophages during sepsis." (PMID 34983946, 2022). "The expression of the transcription factor KLF14 was upregulated in both in vitro and in vivo sepsis models, and the deletion of KLF14 significantly decreased the survival rate of septic mice." (PMID 34983946, 2022). "To further elucidate the possible role of KLF14 in macrophages during sepsis, we assessed the infiltration of macrophages into the septic and normal lungs of WT and KLF14−/− mice." (PMID 34983946, 2022). "Then, we explored the functional effects in vitro and elucidated the mechanism of KLF14 in the immune functions of macrophages in sepsis." (PMID 34983946, 2022). "Male wild-type (WT) and KLF14−/− mice were subjected to endotoxemia induced by intraperitoneal injection and sepsis induced by cecal ligation and puncture." (PMID 34983946, 2022). "Compared with the respective levels in the control group, the mRNA and protein expression levels of KLF14 and the inflammatory factor IL-1β were increased in the PBMCs collected from sepsis patients." (PMID 34983946, 2022). "In addition, the activation of KLF14 by perhexiline conferred protection against sepsis in mice by inhibiting the inflammatory signaling pathway." (PMID 37551728, 2023). "To determine whether KLF14 has clinical significance in septic patients, we checked the expression of KLF14 in sepsis patients." (PMID 34983946, 2022).
Sepsis (continued). "To further understand whether KLF14 can affect immune responses to sepsis by regulating macrophage glycan metabolism, we assessed two main modes of metabolism in macrophages: glycolysis and mitochondrial metabolism." (PMID 34983946, 2022). "To determine whether KLF14 is altered in patients who suffer from sepsis and has clinical significance, we collected PBMCs from sepsis patients and control subjects." (PMID 34983946, 2022). "In addition, pharmacological activation of KLF14 confers protection against sepsis in mice, supporting the therapeutic potential of KLF14 agonists in the treatment of sepsis." (PMID 34983946, 2022). "Moreover, it has been reported that KLF14 is a maternally expressed gene; therefore, we also established female murine sepsis models, and the results showed that the deletion of KLF14 also increased the inflammation level in female sepsis mice." (PMID 34983946, 2022). "The effect of KLF14 on other immune cells in sepsis awaits further investigation." (PMID 34983946, 2022). "Moreover, KLF14 is a maternally expressed gene, and it has been reported that there are significant sex differences in the prognosis of sepsis patients." (PMID 34983946, 2022). "Here, we fully verified our hypothesis through rescue assays and ultimately identified the role of KLF14 in macrophage glycolysis during sepsis." (PMID 34983946, 2022). "Together, these findings suggest that KLF14 may act as a key modulator of the immune response of macrophages by affecting glycolysis during sepsis." (PMID 34983946, 2022). "Furthermore, pharmacological activation of KLF14 conferred protection against sepsis in mice." (PMID 34983946, 2022). "Therefore, we believe that the protective effect of perhexiline in sepsis may depend more on the influence of certain genes that are activated rapidly, such as KLF14." (PMID 34983946, 2022). "Thus, the transcription factor KLF14 is involved in the process of sepsis." (PMID 34983946, 2022). "Indeed, KLF14 may also restrain macrophages from secreting inflammatory factors through the NF-κB pathway during sepsis." (PMID 34983946, 2022). "Previous results suggest that KLF14 may play a clinically significant role in human sepsis." (PMID 34983946, 2022). "Of note, our results indicate that perhexiline can induce the mRNA expression of KLF14 in the lung tissue of mice and significantly prolong the survival of mice with LPS-induced endotoxemia and mice with CLP-induced sepsis." (PMID 34983946, 2022). "Although the underlying molecular mechanism of the KLF14 agonist perhexiline in sepsis was not elucidated in our study, we believe that KLF14 is a potential new therapeutic target for human sepsis, and related clinical trials are warranted." (PMID 34983946, 2022). "Although we established female murine sepsis models, our results did not determine whether KLF14 is affected by sex differences, and further experiments are needed." (PMID 34983946, 2022).
coronary artery disease (5 papers, 2018 to 2025). "Moreover, human genetic studies have shown that variants near the KLF14 gene are strongly associated with T2DM, altered HDL-C and TG levels, and the risk of coronary artery disease." (PMID 37351102, 2023). "We also observed a reduction in the methylation pattern of KLF14 after relaxing practices that may provide a new indicator of the favorable effect on prevention coronary artery disease." (PMID 31450859, 2019).
hepatocellular carcinoma (5 papers, 2020 to 2024). A malignant tumor that arises from hepatocytes. "KLF14 was significantly downregulated in hepatocellular carcinoma (HCC), correlating with poor prognosis, and inhibits the proliferation of HCC cells by modulating cellular iron metabolism via the repression of Iron-responsive element-binding protein 2 (IRP2)." (PMID 39518098, 2024). "LncRNA DGCR5 represses hepatocellular carcinoma cell growth, migration, and invasion through sponging miR-346 to elevate KLF14 expression." (PMID 34420031, 2021). "KLF14 is regulated as a target gene of lncRNA DGCR5 to inhibit the progression of hepatocellular carcinoma (HCC)." (PMID 35570248, 2022).
prostate carcinoma (5 papers, 2021 to 2023). A carcinoma that arises from epithelial cells of the prostate gland. "Research showed that KLF14 relies on MAPK signaling pathways to increase oxidative adaptation in castration-resistant prostate cancer." (PMID 38143751, 2023). "In addition, KLF14 transactivated HMOX1, which encoded haem oxygenase‐1 and enhanced antioxidant properties of prostate cancer cells." (PMID 34031939, 2021). "Oxidative stress activates the expression of Krüppel-like factor 14 (KLF14) via multiple pathways, including the PI3K/Akt, p42/p44 MAPK, AMPK, and protein kinase C pathways, in castration-resistant prostate cancer." (PMID 34405016, 2021).
cervical cancer (4 papers, 2022 to 2023). A primary or metastatic malignant neoplasm involving the cervix. "KLF14-induced S-phase arrest in cervical cancer cells was therefore associated with the presence of the zinc fingers, and the loss of any zinc finger diminished cell-cycle regulation compared with function before mutation." (PMID 38143751, 2023). "Lentiviral infection was used to construct KLF14, KLF14 zinc-finger structural mutations, and empty vector controls in SiHa and HeLa cervical cancer cells." (PMID 38143751, 2023). "We therefore demonstrated a role for KLF14 in regulating the cell cycle in cervical cancer and uncovered its underlying mechanism of action." (PMID 38143751, 2023). "In this study, we explored whether KLF14 is also associated with cervical cancer." (PMID 35570248, 2022). "The KLF14 mRNA expression levels in SiHa, HeLa, C33A, and Caski cervical cancer cell lines were measured (1.470±0.543, 0.636±0.085, 11.053±0.46852, 28.660±0.590, respectively)." (PMID 38143751, 2023). "We used flow cytometry to demonstrate that KLF14 promoted apoptosis of cervical cancer cells, and in our mechanistic exploration, we found that it targets ITGB1 to regulate downstream PI3K/AKT signaling—thus promoting apoptosis." (PMID 38143751, 2023). "Recently, it was shown that KLF14 suppresses the cervical cancer progression by reduction of the cell proliferation and enhancement of the apoptosis through integrin β1 (ITGB1) via the PI3K/AKT signalling pathway." (PMID 36831624, 2023). "KLF14 induced S-phase arrest in cervical cancer cells and inhibited the proliferation of cervical cancer cells in vivo; the induction of S-phase arrest was related to its zinc-finger structure." (PMID 38143751, 2023). "Our group previously employed CCK-8 and colony-formation assays, and subcutaneous tumorigenesis experiments in nude mice to show that KLF14 inhibited the proliferation of cervical cancer cells." (PMID 38143751, 2023). "This showed that KLF14 increases CDK2 mRNA expression by activating the JNK pathway in cervical cancer cells." (PMID 38143751, 2023). "Vivo experiments revealed that KLF14 inhibited cervical cancer cell proliferation (P<0.01) and that p-JNK/JNK, CDK2, and CCNA2 expression levels were augmented in tumours in the overexpression group (P<0.01)." (PMID 38143751, 2023). "KLF14 inhibits the progression of cervical cancer by targeting ITGB1 via the PI3K/AKT signalling pathway." (PMID 36831624, 2023). "Our results showed that tumours in the experimental group weighed less than in the control group (P=0.012) and that KLF14 inhibited the proliferation of cervical cancer cells in vivo." (PMID 38143751, 2023). "After KLF14 overexpression, our statistical distribution of cell-cycle data for cervical cancer cells showed that the G0/G1 phase of the HeLa OE-Ctrl group (P=0.011) and the G2/M phase of the HeLa OE-KLF14 group (P=0.008) were not normally distributed." (PMID 38143751, 2023). "Then, at the cellular level, we verified that the proliferation of KLF14-overexpressing cervical cancer cells was inhibited according to CCK-8 and colony formation assays." (PMID 35570248, 2022). "The effect of KLF14 on the proliferation of cervical cancer cells was verified by Cell Counting Kit-8 (CCK-8) assays, colony formation assays and in vivo experiments." (PMID 35570248, 2022). "This indicated that in most cases, KLF14 expression was low in cervical cancer tissues, but high in paracancer tissues." (PMID 35570248, 2022). "The KLF14 expression level in cervical cancer tissues was lower than that in adjacent tissues in 22 cases and higher than that in adjacent tissues in 7 cases." (PMID 35570248, 2022). "To assess the expression level of KLF14 in cervical cancer tissues, we performed immunohistochemistry analysis of a tissue microarray containing 31 cervical cancer tissues and their adjacent tissues." (PMID 35570248, 2022).
cervical cancer (continued). "ITGB1 also plays an important role in this process, as KLF14 inhibits the progression of cervical cancer by targeting ITGB1 through the PI3K/AKT signalling pathway." (PMID 35570248, 2022). "We also found that ITGB1 reversed the effect of KLF14 on cervical cancer cell apoptosis, resulting in decreased apoptosis." (PMID 35570248, 2022). "The effect of ITGB1 on cervical cancer cell apoptosis was reversed by KLF14, resulting in increased apoptosis." (PMID 35570248, 2022). "In summary, KLF14 inhibits the progression of cervical cancer by targeting ITGB1 via the PI3K/AKT signalling pathway." (PMID 35570248, 2022). "In conclusion, this study confirmed that KLF14 inhibits the proliferation and promotes the apoptosis of cervical cancer cells." (PMID 35570248, 2022). "Mechanistically, ITGB1 expression was significantly downregulated in KLF14-overexpressing cervical cancer cells." (PMID 35570248, 2022). "In general, we believe that KLF14 has an inhibitory effect on the proliferation of cervical cancer cells." (PMID 35570248, 2022). "The results showed that the apoptosis rate of both SiHa cells and HeLa cells in the Lv-KLF14 group was higher than that in the Lv-control group, suggesting that KLF14 can promote the apoptosis of cervical cancer cells." (PMID 35570248, 2022). "Immunohistochemical assays confirmed that the expression of KLF14 in cervical cancer tissues was lower than that in paracancerous tissues." (PMID 35570248, 2022). "As a result, the expression of KLF14 in cervical cancer tissues was lower than that in paracancerous tissues." (PMID 35570248, 2022). "To verify the effect of KLF14 on the progression of cervical cancer in vivo, we used SiHa cell suspensions from the Lv-KLF14 group as a positive control and the Lv-control group as a negative control to construct a subcutaneous neoplasia model in nude mice." (PMID 35570248, 2022). "In this study, we investigated whether KLF14 can inhibit the proliferation and induce S-phase arrest of cervical cancer cells." (PMID 38143751, 2023). "Thus, we observed that KLF14 overexpression augmented the ratio of S-phase cells and reduced the ratio of the G0/G1 phase cells in cervical cancer, inducing S-phase arrest in cervical cancer cells." (PMID 38143751, 2023). "Subcutaneous xenograft studies to explore the effects of KLF14 on cervical cancer cell proliferation in vivo, and western blotting was implemented to measure the expression of CCNA2, CDK2, and the activation levels of the MAPK-signaling pathway proteins in tumours." (PMID 38143751, 2023). "The effect of KLF14 on cervical cancer cell cycle was detected by flow cytometry." (PMID 38143751, 2023). "In summary, this study revealed that KLF14 inhibited the proliferation of cervical cancer cells in vivo, and we for the first time determined that KLF14 induced S-phase arrest in cervical cancer cells and that the action was related to its zinc-finger structure." (PMID 38143751, 2023). "In future studies, our research group will further examine the role of KLF14 and discern its underlying mechanisms of action in various oncological behaviors in cervical cancer, thereby providing a novel foundation for the development of therapeutic drug targets of KLF14." (PMID 38143751, 2023). "In summary, these results suggest that KLF14 plays an inhibitory role in the progression of cervical cancer and may be helpful in the treatment of cervical cancer in the future." (PMID 35570248, 2022). "The effect of KLF14 on cervical cancer cell apoptosis was detected by flow cytometry." (PMID 35570248, 2022). "Therefore, the KLF14 expression level in cervical cancer tissues was lower than that in adjacent tissues." (PMID 35570248, 2022). "We considered whether the effect of KLF14 targeting ITGB1 on the progression of cervical cancer was related to the PI3K/AKT signalling pathway." (PMID 35570248, 2022). "KLF14 inhibited proliferation and promoted apoptosis in cervical cancer cells." (PMID 35570248, 2022).